VWF (von Willebrand factor)
Diseases named in the same sentence as VWF in open-access papers (continued):
Sharing a sentence is not in itself a finding about the gene and the disease.
thrombosis (continued). "VWF not only plays a role in arterial and venous thrombosis, but in atherosclerosis, and thrombosis accompanying malaria, sepsis, and sickle cell anemia, where ADAMTS13 activity is at or near normal levels." (PMID 39445200, 2024). "Subsequent screening revealed that the procoagulant-related protein von vWF plays a crucial role in network regulation along with FBLN5, a protein closely associated with thrombosis." (PMID 38649864, 2024). "This interpretation is consistent with results of a Mendelian randomization analysis that also identified FVIII and vWF as causally related to cardiovascular events such as CAD, venous thrombosis, and ischemic stroke." (PMID 39175055, 2024). "Aptamer ARC1779 primarily inhibits von Willebrand factor (VWF), which causes thrombocytopenia in thrombosis." (PMID 38305844, 2024). "Among them, mutations in ABCA13, FLT1, NRP1, SWAP70 and SLC15A4 are strongly associated with immunity or proliferation, whereas mutations in VWF, SELP and EPHB2 are associated mainly with thrombosis." (PMID 39671267, 2024). "Adjusting for age and sex strengthened the association between high unfolded VWF levels and APS (OR: 8.51; CI:3.26 - 22.2; p<0.001), thrombosis (OR:5.87; CI:2.07 - 16.7, p=0.001) and AID (OR:3.71; CI:1.40 – 9.87; p=0.009)." (PMID 39726607, 2024). "In contrast, excessive vWF activity can contribute to thrombotic disorders such as deep vein thrombosis and pulmonary embolism." (PMID 38649864, 2024). "Taking this into account, the role of vWF develops in connection with thrombosis resulting from significant endothelial damage." (PMID 36980889, 2023). "Von Willebrand factor (VWF) plays a role in primary hemostatic mechanism associated with hemorrhage and thrombosis." (PMID 38066509, 2023). "A total of nine genes with a direct (seven) or indirect (two) link with thrombosis, inflammation, and VWF were found." (PMID 37762470, 2023). "The highest levels of P-selectin, vWF antigen, and F-VIII activity were observed among critically ill patients and were associated with thrombosis, severe disease, lower rates of hospital discharge, and higher mortality." (PMID 37628764, 2023). "ROC curve analysis showed that the cut-off value of vWF activity for venous thrombosis within one year after anticoagulant therapy was 267.5%, and the AUC was 0.742 (95% CI: 0.764-0.921, P < 0.05)." (PMID 37442989, 2023). "Despite elevated VWF levels, VWF function varied substantially, mirroring the clinical picture of thrombosis as well as bleeding symptoms." (PMID 36611985, 2023). "We measured plasma levels of two proteins released by activated endothelial cells, von Willebrand Factor (VWF) antigen and soluble P-Selectin (sP-Sel), and a biomarker of systemic thrombosis, D-dimer." (PMID 35588115, 2022). "In human venous thrombosis, NETs act as fibrous scaffolds for von Willebrand factor (vWF), fibrin, and platelets." (PMID 36093130, 2022). "Microvascular thrombosis, which is also common in SSc, is closely related to the expression of the adhesion molecule vWF on the surface of endothelial cells." (PMID 35733188, 2022). "At the same time, patients with thrombosis had significantly higher VWF immunostaining intensity in the arterial, venous, and arteriolar endothelium than those with pulmonary embolism." (PMID 35215805, 2022). "Some coagulation factors, such as the factor II (FII), the factor VII (FVII), the factor VIII (FVIII), fibrinogen (Fg), and von Willebrand factor (vWF), are in a close relation to the incidence and development of thrombosis and coronary heart diseases." (PMID 35669364, 2022). "Hematologic assessment (i.e., thrombin generation, platelet activation studies, von Willebrand factor) is commonly performed to help manage convalescent patients who have been re-admitted for acute thrombosis." (PMID 33752798, 2021).
thrombosis (continued). "Increased levels of disintegrins and metalloproteases with a thrombospondin type 1 motif, member 13 (ADAMTS-13), and VWF are causative for cardiovascular events in SLE patients, as well as venous thrombosis." (PMID 34461924, 2021). "During thrombosis, hypoxia-induced release of von Willebrand factor (vWF) and p-selectin from the endothelium recruits and activates neutrophils, initiating NETs production." (PMID 35095865, 2021). "Lacking ADAMTS13 enhances the accumulation of large multimers of vWF, vWF–platelet aggregation, and microvascular thrombosis of TTP, leading to low platelet count, ischemia, and organ dysfunction." (PMID 32983137, 2020). "The FeCl3-induced thrombosis model has also been used to verify the role of platelet-derived von Willebrand factor (vWF) in thrombosis." (PMID 33172065, 2020). "Increasing evidence indicates that the interaction between NETs and VWF contributes to arterial and venous thrombosis as well as inflammation." (PMID 33343584, 2020). "Their close molecular relationship is also reflected by the strong correlation we found, so that a clear distinction regarding the individual cause and effect of VWF and FVIII on thrombosis incidence appears to be difficult at present." (PMID 31294335, 2019). "The microbiota-induced TLR2-mediated increase in plasma VWF levels, supported arterial platelet deposition in a ligation injury model of the common carotid artery, a mouse thrombosis model on platelet deposition to exposed subendothelial matrix molecules." (PMID 31847071, 2019). "A new method of targeting vWF to prevent arterial thrombosis involves the use of charged nanoparticles (CNPs)." (PMID 31768485, 2019). "Many studies employing thrombosis models have clearly have demonstrated the key role of VWF in thrombus formation." (PMID 31682263, 2019). "Recently, several multiscale particle-based approaches have been developed to directly incorporate nanoscale vWF molecules with microscale cells in order to tackle thrombosis." (PMID 31768485, 2019). "Given the critical role of vWF in arterial thrombosis, it is a natural potential target for preventing the RPA associated with ischemic events like heart attacks and strokes." (PMID 31768485, 2019). "Lack of VWF cleavage resulting from ADAMTS13 defects leads to diffuse microvascular thrombosis promoted by the increased binding of A1 domain of VWF to its platelet-receptor GPIbα." (PMID 30805339, 2019). "Under supraphysiological shear stress (i.e., ECMO), the immobilized VWF-fHb complex would rapidly capture platelets and lead to thrombosis." (PMID 30175099, 2018). "In vivo, VWF-/- mice were shown to be protected from thrombosis in a deep venous thrombosis model by preventing the adhesion of platelets and leukocytes to the vascular endothelium." (PMID 28249049, 2017). "In the clinical setting, elevated levels of VWF and FVIII have been reported associated with an increased risk of venous thrombosis; however, this effect was due to increased FVIII levels." (PMID 25297919, 2015). "Individuals with the ABO A1 and B alleles were found to have a lower rate of vWF clearance, thus higher plasma levels of vWF and FVIII, and higher risk for thrombosis." (PMID 26275671, 2015). "In this review, we will summarize the recent advances on the molecular mechanisms involved in the interaction of VWF with GPIb-IX-V and its role on arteriolar but also in venous thrombosis." (PMID 25297919, 2015). "While the importance of VWF/GPIbα interaction in arterial thrombosis is well-established and accepted, the role of this interaction in venous thrombosis has long remained unclear with conflicting conclusions from various in vitro models." (PMID 25297919, 2015). "Altogether these new findings clearly show that VWF is a component critical in venous thrombosis and that VWF is a potential target for venous thrombosis treatment." (PMID 25297919, 2015).
thrombosis (continued). "Several studies have provided compelling evidence of the relevance of VWF levels in the pathogenesis of macrovascular thrombosis, especially in the brain circulation." (PMID 23383177, 2013). "Perhaps it is significant that a role for GPIb and VWF has been proposed in venous thrombosis while the ability of GT platelets to bind to fibrin is well known." (PMID 23346430, 2012). "Adequate baseline and post-treatment data were available on 26 patients, but two were excluded due to an unexplained borderline-low vWF antigen level at baseline or the occurrence of a line-related thrombosis during CYT997 infusion." (PMID 20733579, 2010). "In these studies, plasma VWF alone was sufficient to support bleeding time and the development of occlusive arterial thrombosis in the Folts arterial stenosis and injury model." (PMID 22091368, 2010). "In this study, we endeavored to provide mechanistic insight into the initiation of venous thrombosis, with an emphasis on understanding the role of VWF, and how this might explain the proclivity for thrombosis to develop in venous valve pockets." (PMID 39908367, 2025). "In patients with Graves’ disease, an additional factor is the prothrombotic state, characterized by elevated factor VIII and von Willebrand factor, which may explain the occurrence of coronary thrombosis in a subset of patients (≈11%)." (PMID 41301686, 2025). "The role of the vWF in thrombosis differs across vascular beds." (PMID 41007843, 2025). "High levels of vWF:Rco indicate increased platelet aggregation and microvascular thrombosis." (PMID 40990987, 2025). "Our model could be readily incorporated into a continuum model of high shear thrombosis by coupling the configuration tensor to an advection–diffusion equation which tracks the concentration of VWF in the flow." (PMID 38592600, 2024). "Our analysis of the link between true flap loss and VWF antigen concentration did not include the distinction between arterial and venous thrombosis of the anastomosis, which has been reviewed in previous studies." (PMID 39336896, 2024). "VWF pro-peptide levels above the 90th percentile were significantly associated with APS, thrombosis and AID in the crude model (OR: 5.94, OR: 6.49, and OR 6.44, respectively; all p<0.001) and in the fully adjusted model (OR:5.19, OR:6.21, and OR:5.70; p<0.001)." (PMID 39726607, 2024). "Firstly, increased levels of vWF, fibrinogen, and factor VIII may trigger venous thrombosis in particularly susceptible women during early pregnancy." (PMID 38822265, 2024). "Odds ratio for APS, thrombosis or AID at VWF levels above the 90th percentile." (PMID 39726607, 2024). "The blood protein Von Willebrand factor (VWF) is critical in facilitating arterial thrombosis." (PMID 38592600, 2024). "Besides TTP, an imbalance in the VWF:ADAMTS-13 axis was linked to ischemic stroke and coronary occlusion and to increased risk for arterial and deep-vein thrombosis." (PMID 38399555, 2024). "Increased levels of procoagulant factors, such as F VIII, F IX, fibrinogen, and Von Willebrand factor (vWF), have been found in hyperthyroid patients, with high levels of free Thyroxine (FT4) being associated with the risk of venous thrombosis, up to an odds ratio of 2.2." (PMID 36064879, 2023). "Notably, FGA, VWF and MPRIP variants correlated with intravascular coagulation and thrombosis, as well as impaired mechanosensory functions of osteocytes." (PMID 36813871, 2023). "In addition, von willebrand factor (VWF) involved in intrarenal thrombosis was suggested to mediate the deterioration of renal function." (PMID 37853335, 2023). "For prediction of thrombosis; VWF at cutoff > 257.7 has 83.3% sensitivity and 83.3% specificity." (PMID 36138306, 2023). "Moreover, SIRT1/FOXO1 signaling pathway has been identified as a promising target to prevent VWF-mediated arterial thrombosis." (PMID 37415610, 2023).
thrombosis (continued). "A thrombotic microangiopathy characterized by systemic microvascular platelet aggregation due to failure in degradation of von Willebrand factor (vWF), TTP can predispose patients to both thrombosis and hemorrhage due to marked thrombocytopenia – a relative contraindication to SAC." (PMID 37206280, 2023). "Furthermore, we found that elevated levels of factor VIII and VWF and decreased levels of ADAMTS-13 were associated with an increased incidence of thrombosis in PCR positive patients." (PMID 35482749, 2022). "However, the results of published studies concerning the relationship between venous thrombosis and VWF are contradictory." (PMID 35215805, 2022). "We reported elevated levels of an acute-phase reactant and an indicator of vascular injury, such as VWF, that might be a marker of chronic inflammation and atherosclerosis in PV patients with thrombosis." (PMID 35626232, 2022). "A number of studies report the prevalence of other hereditary thrombophilia, such as hyperhomocysteinemia (HHC), increased levels of von Willebrand factor (VWF), and plasminogen deficiency, and their role in the development of thrombosis in patients with MINOCA." (PMID 36474151, 2022). "For thrombosis-associated parameters, samples collected at baseline presented with a significant positive correlation between TMAO and RIS (R Spearman = 0.219, p = 0.024) and between TML and VWF (R Spearman = 0.194, p = 0.046)." (PMID 35268516, 2022). "Using the rhADAMTS13 protease to specifically cleave vWF, thrombolysis was observed in animal thrombosis models, and the combination of rhADAMTS13 and DNase I effectively improved myocardial infarction by reducing the interaction of vWF with neutrophils and NETs in myocardial tissue of mice." (PMID 35711663, 2022). "Furthermore, the plasma samples collected from patients at the post-LVAD bleeding events activated more endothelial cells to express PS and to release VWF, whereas those from patients with thrombosis induced permeability at similar levels to pre-LVAD samples." (PMID 35411318, 2022). "According to our results and previous studies, the crosstalk between NETs and VWF may be critical in thrombosis in CVST patients." (PMID 35869501, 2022). "Platelet- and VWF-rich thrombi demonstrate greater resistance to thrombolytic therapies suggesting that treatment options are limited after established microvascular thrombosis in severe COVID-19 infection." (PMID 35087853, 2021). "However, abnormal accumulations of vWF caused by deficiency of plasma ADAMTS13 trigger intravascular platelet aggregation and micro thrombosis leading to a vascular disease, thrombotic thrombocytopenic purpura (TTP)." (PMID 34868193, 2021). "The effect of anfibatide on platelet adhesion, aggregation, thrombus formation, and thrombolysis at different shear rates was assessed using an in vitro thrombosis model in perfusion chambers coated with collagen, on which soluble VWF from blood quickly anchors." (PMID 34083615, 2021). "An O-type blood-related variant might decrease the activity of glucosyl transferase, reduce concentration of vWF and factor VIII, and thus reduce risk of MI and venous thrombosis." (PMID 32293292, 2020). "A polymorphism in SLC44A2 (rs2288904-A) present in 22% of the population causes an R154Q substitution in an extracellular loop of SLC44A2 that is protective against venous thrombosis results in severely impaired binding to both activated αIIbβ3 and VWF-primed platelets." (PMID 32314961, 2020). "The RT-qPCR assays indicated that DS–SQ (10:1) could cure the PHZ-induced thrombosis by downregulating the expression of PKCα, PKCβ, fga, fgb, fgg and vWF in zebrafish." (PMID 32322295, 2020). "In addition, VWF was reported to be involved in intrarenal thrombosis leading to the deterioration of renal function." (PMID 32778679, 2020). "The vWF:Ag/ADAMTS-13 ratio increased by 57.7% before thrombosis." (PMID 33292287, 2020).
thrombosis (continued). "As the crucial protein for arterial thrombosis, vWF targeting may provide a method for selectively preventing stenotic occlusion without concomitant bleeding." (PMID 31768485, 2019). "Via the activation of pattern recognition receptors (PRRs) on platelets and endothelial cells, MAMPs promote arterial thrombosis and stimulate the synthesis of prothrombotic von Willebrand factor (VWF) in the hepatic endothelium, along with increased FVIII plasma levels." (PMID 31847071, 2019). "What aspects of vWF function play a different role in arterial thrombosis compared to hemostasis?" (PMID 31768485, 2019). "In the European Concerted Action on Thrombosis and Disabilities (ECAT) study, in stable patients with angiographically documented coronary artery disease (CAD), higher levels of VWF:antigen (VWF:Ag) were independently associated with an increased incidence of MI and sudden death." (PMID 28634421, 2017). "It has been addressed that patients with PNH have higher level of vWF, as being demonstrated in our study as well, additionally the level of factor VIII also higher in PNH patients, and higher level of vWF and factor VIII is related with higher risk of thrombosis." (PMID 29190926, 2017). "Erythrocyte adhesion to von Willebrand factor may be particularly relevant for venous thrombosis, which is characterized by the formation of erythrocyte-rich thrombi." (PMID 28249049, 2017). "Thus, our data strongly suggest a critical role of luminal VWF fibers in determining the occurrence of thrombosis and cancer metastasis." (PMID 27602496, 2016). "A recent study by Dmitrieva and Burg proved that high salt might increase the secretion of von Willebrand factor (vWF) in vascular endothelial cells, resulting in hypercoagulability and thrombosis." (PMID 26078816, 2015). "While the roles of GPIb-IX-V and VWF in thrombus formation was already well-established in flow chambers studies in conditions of high shear rates, mice deficient for VWF and GPIb-IX-V were essential to precisely determine the contribution of VWF in atherothrombosis and in venous thrombosis in vivo." (PMID 25297919, 2015). "Although we found a significant difference in vWF between venous recurrences and controls, the wide distribution of values prevents an accurate discrimination between these two, limiting vWF as a predictor for venous thrombosis." (PMID 25814984, 2015). "Recent studies in animal models of venous thrombosis support a role for VWF at low shear stresses." (PMID 23355889, 2013). "Whether targeting VWF carbohydrate modifications might provide clinically meaningful opportunities for treatment of thrombosis and MI is an open question." (PMID 23133757, 2012). "However, only few studies have examined the effect of VWF levels on the association between ABO blood type and thrombosis." (PMID 17894864, 2007). "Patients without previous thrombosis with vWF: Ag > 120% had a higher risk of incident thrombosis." (PMID 41085687, 2025). "•Plasmin-cleaved VWF may reflect a response to ongoing microvascular thrombosis." (PMID 41035784, 2025). "Furthermore, leveraging the summary data from the GWAS catalog, we revealed significant enrichment of VTE-related genes in diseases such as thrombosis and ischemic stroke as well as in hemostatic factors and hematological phenotypes such as D-dimer levels and von Willebrand factor (vWF) levels." (PMID 38561338, 2024). "In this review, the incidence of symptomatic PICC related thrombosis in patients was ranked from low to high as follows: O (3.30%), A (4.92%), B (5.20%), and AB (6.58%), which corresponded to the synergistic relationship between vWF levels among different ABO blood types." (PMID 38950056, 2024). "Interestingly, high unfolded VWF levels were significantly associated with non-APS thrombosis as well, although with a lower OR of 5.9." (PMID 39726607, 2024).